GFAP (glial fibrillary acidic protein)
Diseases named in the same sentence as GFAP in open-access papers (continued):
Sharing a sentence is not in itself a finding about the gene and the disease.
Stroke (continued). "We used GFAP-TK mice to selectively ablate neural stem cells prior to stroke." (PMID 37816732, 2023). "In a recent study of 272 patients (203 ischemic strokes, 60 ICH, and 9 stroke mimics), it was shown that prehospital plasma GFAP concentrations (pg/mL) could differentiate patients with ischemic stroke from those with ICH." (PMID 37892701, 2023). "In the two experiments with Wistar rats, there was also an increase in laminin expression and in the number of activated microglia, together with a significant increase in AQP4 and GFAP levels in the stroke model compared with the AD plus stroke model at 24 h and up to 28 days later." (PMID 35743229, 2022). "On day 56 post stroke, rat brains were freshly obtained and examined using human NeuN and GFAP primers to elucidate whether the HUMSCs grafted had differentiated into neuronal cells or astrocytes in the cerebral cortex of rats with chronic stroke." (PMID 35328574, 2022). "We evaluated the effect of polyphenols on GFAP protein levels in obese mice exposed to stroke." (PMID 35624723, 2022). "GFAP is the main intermediate filament protein almost exclusively expressed in astrocytes and is involved in the maintenance of cytoskeletal structures and functions and in various pathological processes, such as trauma, stroke, and neurodegenerative diseases." (PMID 36552122, 2022). "An additional source of GFAP leakage to the CSF may be reactive astrocytes and gemistocytes found in stroke and in cortical microinfarcts." (PMID 36009416, 2022). "GFAP, an intermediate filament protein, is mainly expressed in astrocytes and its plasma level has been proposed as a biomarker for nervous system injury in traumatic brain injury and stroke." (PMID 35982410, 2022). "To determine the effect of blocking C3d+/GFAP+ A1 astrocyte formation on infarction and neurobehavioral recovery in stroke mice, we examined infarct volume and neurobehavioral parameters, including the mNSS score, rotarod test and hanging wire test, in tMCAO mice." (PMID 35656116, 2022). "Here, we also showed that photothrombotic stroke causes an increase in the level of γ-secretase proteins PS1 and nicastrin mainly in astrocytes and the administration of the inhibitor reduces the level of GFAP." (PMID 36289917, 2022). "At day 7 post-stroke, Ascl1 began to be detectable in GFAP positive astrocytes." (PMID 36535938, 2022). "Finally, previous studies have found that GFAP and S100B correlated with stroke severity and outcome." (PMID 36176549, 2022). "In addition, GFAP was found to be significantly increased in hemorrhagic stroke patients, as compared to ischemic stroke and all non-stroke patients (434 ± 566 and 95 ± 226 pg/mL, p-value < 0.01)." (PMID 34206615, 2021). "Some animal studies have shown that transplanted MSCs can migrate to injured sites of the brain, differentiate into neuron-like cells expressing microtubule association protein-2 (MAP2) and glial fibrillary acidic protein (GFAP), and improve neurological function after stroke and spinal cord injury." (PMID 33968150, 2021). "The development of a point-of-care device able to measure D-dimer and GFAP rapidly (e.g., <10 min), as well as to automatically combine field-collected stroke severity scales in an algorithm, would be required to implement our diagnostic strategy in the clinic." (PMID 34206615, 2021). "Here, we report a platform for biosensing based on chelated Eu3+ against a range of proteins including biomarkers of cardiac injury (human myoglobin), stroke (glial fibrillary acidic protein (GFAP)), inflammation (C-reactive protein (CRP)) and colorectal cancer (carcinoembryonic antigen (CEA))." (PMID 33513673, 2021). "Herein, we have demonstrated that a biomarker panel composed of both D-dimer and GFAP, when combined with clinical stroke scales, may serve as a valuable tool for the specific identification of stroke patients with LVOs." (PMID 34206615, 2021).
Stroke (continued). "EE exposure increased GFAP expression in stroke lesioned rats leading to cognitive improvement." (PMID 34572529, 2021). "In addition, GFAP was significantly increased in hemorrhagic stroke, as compared to all the other suspected stroke patients (1043 ± 2581 and 66 ± 130 pg/mL, p-value < 0.05)." (PMID 34206615, 2021). "While the majority of studies which found significant reductions in IBA+ and GFAP+ cells in the acute and chronic stroke environment administered the therapeutic at subacute time points (∼7 days post-MCAO), the latter study administered cells at an acute (24 h) timepoint." (PMID 33796535, 2021). "These analyses suggest that the presence in plasma of GFAP, a known biomarker of stroke and traumatic brain injury, could be due to brain injury in children with SCD and SCI." (PMID 33915030, 2021). "Accordingly, the combination of D-dimer and GFAP with stroke scales may provide a simple and highly accurate tool for identifying LVO patients, with a potential impact on time to treatment." (PMID 34206615, 2021). "Furthermore, donor cell survival increases and stroke injury site declines in glial fibrillary acidic protein (GFAP) +cells, proinflammatory cytokines, and CD68." (PMID 34572529, 2021). "Therefore, to determine the long-term characteristics of astrogliosis in secondary thalamic injury, we compared GFAP immunoreactivity in mice at 6 weeks and 2 years post-stroke (young mice at the time of stroke)." (PMID 34131204, 2021). "However, quantification revealed more wide-spread GFAP-positive areas in Stroke-HIF-1 LoF animals compared to HIF-Ctrl mice." (PMID 34046769, 2021). "Additionally, a decrease (p<0.05) in the GFAP intensity and percentage area GFAP in the CC was observed in the rGDF11 treated group compared to vehicle-treated stroke mice." (PMID 32365331, 2020). "The relationship between poorer neurological outcomes and systemic inflammation during stroke has also been highlighted, as patients who developed an infection following their stroke were more likely to have MBP and GFAP-specific T cells 3 months post-stroke; associated to a Th1 response." (PMID 33173502, 2020). "Double immunostainings with antibodies against β-gal and neuronal (NeuN), astrocytic (GFAP) or microglial (CD11b) markers identified the presence of the EphA4/β-gal fusion protein in neurons at 2 weeks and 3 weeks after experimental stroke in EphA4LacZ mice." (PMID 31814004, 2020). "Besides its neuroprotective effect, PACAP also reduces reactive astrogliosis as shown by its ability to inhibit stroke induced GFAP and VIM expression." (PMID 33551991, 2020). "In CADASIL patients, plasma NfL can be a promising biomarker for monitoring incident stroke, whereas GFAP may have a role in cerebral hemorrhage." (PMID 32321529, 2020). "When plotting the ROC curve, plasma NfL and GFAP remained the only two plasma biomarkers that had ability in predicting incident stroke (AUC = 0.783 and 0.742 for NfL and GFAP, respectively, both p < 0.05) or ICH (AUC = 0.798 and 0.782 for NfL and GFAP, respectively, both p < 0.05)." (PMID 32321529, 2020). "Moreover, in a prospective follow-up, higher NfL was predictive of incident stroke, and GFAP mainly predicted cerebral hemorrhage." (PMID 32321529, 2020). "Interestingly, the number of GFAP-positive processes correlated positively with perivascular AQP4 expression in WT animals after stroke but negatively in Cav-1 KO mice." (PMID 32523952, 2020). "In addition, there are premises indicating GFAP value in determining outcome prognosis and neurological status of stroke patients." (PMID 31701356, 2020). "We further characterized the in vivo profile of surviving drNPCs (HuNu+ or STEM121+ cells) at 32 days post-stroke using immunostaining for Sox2 and Nestin (undifferentiated NPCs), GFAP (astrocytes), TUJ1 (immature neurons), NeuN (mature neurons), and Olig2 (oligodendrocytes)." (PMID 30747366, 2020).
Stroke (continued). "A significant increase in GFAP in the EcoHIV group was observed at days 4, 7, and 14 post-stroke." (PMID 31043599, 2019). "Also, CSF levels of GFAP are known to differentiate between patient with ischemic stroke and healthy individuals within the first 24 hours after injury, and GFAP correlates to severity of stroke." (PMID 31693684, 2019). "Additionally, elevated GFAP and Tau has been reported in the plasma of patients who suffered from trauma, stroke, and Alzheimer’s disease." (PMID 31311947, 2019). "However, no APC signal was detected in glial fibrillary acidic protein (GFAP)+ astrocytes in the ischemic brain in our preclinical model of stroke." (PMID 31226122, 2019). "Computerised reconstructions of immunostained sections map the extent of the neuronal damage (loss of MAP-2 or NeuN signal) and its spatial relation with post-stroke glial (GFAP for astrocytes, Iba1 for microglia, MBP-1 for oligodendrocytes) and vascular (CD31 for endothelial cells) reactions." (PMID 30679481, 2019). "Conversely, in our study, GFAP levels were increased in hyperglycemic stroke rats." (PMID 31315686, 2019). "The content of both vimentin and GFAP at 7 days after stroke induction was substantially increased (to 210% and 137% respectively) in the samples from minocycline-treated rats compared with those injected with vehicle, indicating an increase in at least some aspects of reactive astrogliosis." (PMID 30626393, 2019). "Similar numbers of these cells were detected around the stroke lesion in GFAP-/-Vim-/- and WT mice." (PMID 29401502, 2018). "Interestingly, after adult stroke in a preclinical model, increased GFAP expression was found in the ependymal lining, and EMC were affected, but hydrocephalus did not develop." (PMID 30319361, 2018). "Immunohistochemical analysis of lesioned tissue sections (ipsilateral side) established neuronal degeneration in the infarct region with immunofluorescence analyses highlighting GFAP expression, the astrocyte marker, strongly localized within the PL-GM, indicating astrogliosis post stroke." (PMID 30283295, 2018). "We observed activated microglia/macrophages and increased GFAP immunoreactivity in the thalamus still at 4 mo post-stroke, and indeed, also in the intraluminal MCAo model microglial activation in the thalamus has been reported to be long-lasting, for up to 6 mo post-stroke." (PMID 29766045, 2018). "Upregulated GFAP expression occurs in the damaged area after neonatal HI and stroke." (PMID 29568769, 2018). "In the present study, we counted the number of GFAP-positive astrocytes in stroke area." (PMID 29497380, 2018). "The upregulation of GFAP during astrogliosis after stroke is a spontaneous response to CNS insults." (PMID 29075181, 2017). "The results showed that adjudin could significantly reduce the number of GFAP+ cell both at 4 and 7 days after stroke, indicating that astrocyte activation could be attenuated by adjudin." (PMID 29311941, 2017). "Further, PEG-IGF-I can enhance functional recovery post-stroke, in part via an increase in axonal sprouting, improved synaptic plasticity, altered GFAP expression and increased neuroblast migration in both young and aged mice, mechanisms that are all required to aid rehabilitation of stroke victims." (PMID 28325900, 2017). "Previous evidence suggests that the nestin-positive progenitors may also give rise and differentiate into GFAP-positive astrocytes; we next investigated the cellular expression/induction patterns of nestin after stroke." (PMID 28253906, 2017). "Post-stroke saline-treated animals displayed a threefold higher serum level of GFAP (12.52 ± 3.11 ng/ml) as compared to post-stroke NaB-treated group (4.62 ± 0.84 ng/ml, n = 6, p = 0.0175, two-way ANOVA and Tukey’s multiple comparison) at 2 days, indicating NaB treatment attenuated BBB disruption." (PMID 27905989, 2016).
Stroke (continued). "Additionally, immune responses against myelin basic protein (MBP) and glial fibrillary acidic protein (GFAP) have been associated with larger cerebral infarctions and increased the likelihood of worse outcome in stroke patients." (PMID 26742037, 2016). "Furthermore, a previous report showed co-localization of Ngb and GFAP in glia from human brains after stroke." (PMID 27672379, 2016). "The present study measured serum concentrations of ubiquitin C-terminal hydrolase (UCH-L1) and glial fibrillary astrocytic protein (GFAP) in acute stroke patients and healthy controls and investigated their relation to stroke severity and patient characteristics." (PMID 27074724, 2016). "Following the onset of stroke, astrocytes keep changing their structure and function as indicated by the expression of GFAP and AQP4, which determine a conversion of the intracellular edema into extracellular edema in the lesion core while forming a shell of swollen astrocytes at the penumbra." (PMID 27242440, 2016). "Furthermore, stroke patients with acquired infection appeared to present immune responses against myelin basic protein and glial fibrillary acidic protein, and have worse outcomes compared to stroke patients with no infection." (PMID 27923376, 2016). "In addition, studies of the role of neurogenesis in several behavioral and disease models that have been developed in rats, eg, addiction and stroke models, should be able to move forward more quickly in GFAP-TK rats than in equivalent mice." (PMID 27257630, 2016). "GFAP may also be important in the differential diagnosis of various types of stroke, which is clinically relevant as immediate treatment of stroke depends on whether the stroke is ischemic or hemorrhagic." (PMID 27468268, 2016). "Studies in our laboratory, however, have recently found that Fasudil treatment commencing three days after stroke indeed modulates reactive gliosis to reduce glial scarring in rats, as evidenced by reduced GFAP staining and the adoption of less reactive morphologies up to 28 days (unpublished data)." (PMID 26927079, 2016). "Our data show that Smad1 deletion affects several aspects of astrocytic function, which may contribute to neuroprotection against stroke: i) GFAP expression is elevated in astrocytes in uninjured Smad1 cKO mice." (PMID 26317208, 2015). "We show that stroke considerably increased GFAP+ neural stem cells at the center of the pinwheel structure composed of ependymal cells, and that their GFAP+ elongated processes were in direct contact with augmented-blood vessels just beneath the ependymal layer in the V/SVZ niche." (PMID 25437857, 2014). "Astrocytes activated by stroke have multiple thick GFAP+ processes." (PMID 25437857, 2014). "Stroke substantially increased the number of glial fibrillary acidic protein (GFAP) positive neural stem cells that are in contact with the cerebrospinal fluid (CSF) via their apical processes at the center of pinwheel structures formed by ependymal cells residing in the lateral ventricle." (PMID 25437857, 2014). "Anti-GFAP autoantibodies have been preliminarily reported in other human disorders, such as in patients with Alzheimer’s disease or other dementias, stroke, diabetes, neurological disorders, multiple sclerosis, autism and lead-exposed workers." (PMID 24667434, 2014). "In view of the potential use of GFAP as a diagnostic marker of acute ICH, the present investigation aims at providing a cursory overview of GFAP levels in a broad and rather unselected spectrum of neurological conditions and diseases, other than stroke, brain tumor and traumatic brain injury." (PMID 23626774, 2013). "All other diseases that may sporadically lead to increased GFAP values, e.g. severe bacterial meningitis, can hardly be considered as a relevant “stroke mimic”." (PMID 23626774, 2013). "In manifest stroke serum S100B levels described a decelerated increase compared with GFAP." (PMID 23509668, 2013).
Stroke (continued). "Notably, we previously reported a correlation between BDNF levels (ELISA tests) and GFAP expression (a marker of astrocytes activation) in stroke rats." (PMID 22962604, 2012). "In 2024, proteomic analysis revealed oxidized GFAP fragments in astrocyte-derived exosomes that could enter the circulation and correlate with stroke severity, implying astrocytes’ redox state is related to circulating stroke severity biomarkers." (PMID 41303325, 2025). "Additionally, the Appalachian stroke patients had higher GFAP." (PMID 41306424, 2025). "The slower release of GFAP in ischemic stroke is attributed to the initial preservation of brain cell structure and the blood–brain barrier, with cell necrosis and lysis typically occurring 6–12 h after vessel blockage, leading to a delayed peak in GFAP levels around 48–72 h post-stroke onset." (PMID 40142325, 2025). "In our literature, we found that elevated GFAP concentrations were related to the presence of depression after ischemic stroke, which indicated that Neuroinflammatory response may be involved in post-stroke complications." (PMID 40421099, 2025). "Another proposed mechanism is that GFAP may diffuse from the cytosol of injured astrocytes across the blood–brain barrier which is altered and can become ‘leaky’ or damaged in the context of many types of dementia, traumatic brain injury and stroke." (PMID 39289040, 2025). "Our objective was to determine the diagnostic utility of glial fibrillary acidic protein (GFAP) and ubiquitin C-terminal hydrolase L1 (UCH-L1) in the emergency department to identify and differentiate acute stroke within 4.5 h of symptom onset in patients admitted with a stroke code alert." (PMID 40649119, 2025). "In the present study, we demonstrated that AAV-pGFAP-CasRx-Ptbp1 crossed the BBB and generated new mCherry/NeuN double-positive neuron-like cells, its origin could be mCherry/GFAP double-positive astrocyte-like glia, in the hippocampus of post-stroke dementia mouse model." (PMID 39227632, 2024). "Here, we confirmed the presence of GFAP in EVs, which could be a step forward in stroke research." (PMID 38891912, 2024). "Moreover, because a large number of activated astrocytes (GFAP+) were arranged radially around the infarcted core on day 3 after stroke, the infarct core and peri-infarct area could be clearly distinguished." (PMID 37253754, 2023). "Additionally, they reported significant increases in GFAP+ area shape perimeter, major axis length, and mean radius and a significant decrease in solidity in the ipsilateral hemisphere stroke subjects compared to non-stroke subjects." (PMID 37760829, 2023). "Also, GFAP staining indicated a denser gliallesion barrier in mice with severe stroke." (PMID 36606595, 2023). "Glial proteins such as glial fibrillary acidic protein (GFAP), and S100β, which are both structural astrocytic proteins, are two very promising blood biomarkers that could be indicative of stroke in patients presenting with symptoms of acute neurological dysfunction." (PMID 35813155, 2022). "Our study demonstrated that stroke-induced C3d+/GFAP+ A1 astrocytes disrupt blood-brain barrier integrity and that blocking C3d+/GFAP+ A1 astrocyte formation using semaglutide attenuates brain injury, suggesting the detrimental role of C3d+/GFAP+ A1 astrocytes in stroke." (PMID 35656116, 2022). "While the GFAP and CHI3L1 levels are known to be increased in strokes, and the GFAP elevation may help differentiate intracranial haemorrhage from ischemic stroke, the correlation of the two astroglial markers with CSVD severity and other CSVD markers remains uncertain." (PMID 36009416, 2022). "However, the different outcome for the two cytoskeletal proteins might reflect a greater sensitivity of vimentin compared with GFAP content in detecting the treatment-induced changes following photothrombotic stroke." (PMID 34332596, 2021).